ASXL1 (ASXL transcriptional regulator 1)
Diseases named in the same sentence as ASXL1 in open-access papers (continued):
Sharing a sentence is not in itself a finding about the gene and the disease.
cancer (84 papers, 2013 to 2026). A tumor composed of atypical neoplastic, often pleomorphic cells that invade other tissues. "We find that the cancer-related truncated variants comprising residues 1-645 and 1-591 of ASXL1 (ASXL11-645 and ASXL11-591) retain BRD4 binding function, with ASXL11-645 showing an enhanced ability to recruit BRD4 to promoters of ASXL1 target genes." (PMID 41702923, 2026). "Detailed genetic information for AML-ASXL1 samples at the ASXL1 variant sites are provided with alternate allele read, total read, cancer allele frequency, ExAC frequency, and variant registration in dbSNP or COSMIC databases." (PMID 39614348, 2024). "ASXL1 is frequently mutated in cancer and haematological malignancies and correlates with poor prognosis." (PMID 37872885, 2023). "Somatic truncating variants in ASXL1 are associated with age-related clonal hematopoiesis as well as various cancers." (PMID 35361921, 2022). "It has been known that the activity of BAP1 is critical for the maintenance of the protein stability of the additional sex combs-like protein ASXL1-3, including CTD-truncated ASXL1 variant in cancer." (PMID 35194152, 2022). "Cancer-associated BAP1 mutations that inhibit the interaction between ASXL1/2 and BAP1 and impair DUB activity result in deregulated cell proliferation." (PMID 36068610, 2022). "Individuals with BOS have been reported to have Wilms tumor, suggesting that germline ASXL1 mutations increase the risk for certain cancers." (PMID 35361921, 2022). "The DNMT3A, TET2 and ASXL1 genes had the most mutation sites in different cancer types from the Chinese populations." (PMID 34658138, 2021). "Most cancer-associated ASXL1 mutations enhance the catalytic function of BAP1, and therefore decrease levels of H2AK119Ub." (PMID 33105797, 2020). "Beyond cancer, de novo truncating mutations in ASXL1, ASXL2, and ASXL3 have separately been identified in Bohring–Opitz, Bainbridge–Ropers, and related syndromes." (PMID 33105797, 2020). "Collectively, the most frequently mutated cancer myeloid genes were ASXL1 (47%), TET2 (37%), RUNX1 (27%) and SRSF2 (17%)." (PMID 30787430, 2019). "BAP1 and ASXL1/2 undergo both missense and nonsense mutations in various cancers and exhibit hallmarks of haploinsufficiency, whereby mutations even in a heterozygous form have deleterious effects." (PMID 30258054, 2018). "Most cancer-associated ASXL1 mutations give rise to truncated proteins that retain the amino-terminal BAP1 (BRCA1 associated protein 1)-interacting region of ASXL1, but lose the carboxy-terminal PHD domain." (PMID 28055972, 2017). "Comparative structural and biochemical analyses of full-length ASXL1 and truncated cancer-associated ASXL1 mutations could shed light on their functional consequences and the molecular mechanisms underlying ASXL1 mutations in MDS and AML." (PMID 40562788, 2025). "Cancer-associated genes of the locus include ASXL1, DNMT3B, BCL2L1, TPX2, KIF3B and POFUT1." (PMID 34577783, 2021). "As this patient displayed a cancer-associated constitutional mutation in the tumor suppressor ASXL1, this finding could indicate an underlying molecular aberrancy worthy of follow-up studies." (PMID 32519264, 2021). "The mammalian homologs of these proteins (BAP1 and ASXL1/2/3, respectively), are frequently mutated in various cancer types, yet their precise functions remain unclear." (PMID 30664650, 2019). "Biological variables associated to a high risk of progression included CIP2A levels, the expression levels of the polycomb group BMI1 gene, the activation of beta-catenin, specific gene signatures, and mutations in cancer-associated genes such as ASXL1, IKZF1, RUNX1, SETD1B, GATA2, MLL, and UBE2A." (PMID 31709190, 2019).
cancer (continued). "In human myeloid malignancies, inactivating mutations of ASXL1 and TET2 often occur together in the same patient's malignant cells, suggesting that loss of these two tumor suppressors may act synergistically in myeloid transformation." (PMID 31064769, 2019). "Here, we identify a high level of genetic correlation between ASXL1 and the major transcriptional activator BRD4 in cancer cells and characterize the molecular mechanism underlying this correlation." (PMID 41702923, 2026). "Among cancer patients receiving ICB therapy, those with ASXL1 insertion mutations showed longer survival, as ASXL1 disruption provided CD8+ T cells with a selective survival benefit after PD-L1 treatment." (PMID 40093905, 2025). "Similar to the NSCLC validation cohort, patients with TET2-mutant CHIP from the pan-cancer cohort had the highest frequency of TI-CH (33%, 381/1191), followed by ASXL1-mutant (32%, 124/392), DNMT3A-mutant (25%, 926/3,753), and PPM1D-mutant CHIP (13%, 83/622)." (PMID 40267425, 2025). "The copy number variant (CNV) on chromosome 20q11.21 identified in hiPSCs encompassed the cancer-related gene ASXL1, as per the ClinVar database." (PMID 38256178, 2024). "Eight of the cis-CSCE lie in cancer genes on our Tier 3 list, including ASXL1 (qCSCE = 1.04 × 10−2;rhoCSCE = −0.371) and ETV6 (qCSCE = 2.41 × 10−2; rhoCSCE = 0.386)." (PMID 37377903, 2023). "Among the 15 canonical genes associated with CH, our cancer patients had mutations in CHEK2, DNMT3A, ASXL1, PPM1D, and TET2 only." (PMID 35428225, 2022). "All three genes from this locus that are listed as cancer-related at OncoKB knowledgebase (ASXL1, DNMT3B, BCL2L1) are amplified in the 12 cell lines." (PMID 34577783, 2021). "CNV of ASXL1 was first queried across cancer types and ACC was amongst top cancers that harbored ASXL1 gain." (PMID 34536950, 2021). "ASXL1 and EP300 are both involved in chromatin remodelling, but little is known about the functional roles of the disordered regions targeted by cancer mutations." (PMID 33806614, 2021). "Although three genes, DNMT3A, ASXL1 and TET2, are hot genes, CH mutations also appear in other genes, particularly some driver genes that are indicators for cancer therapy." (PMID 34658138, 2021). "Of the many mutations that characterize myeloid malignancies, some (TET2, ASXL1) can initiate a preleukemic clone, whereas others (MPL, JAK2) are phenotypic lesions that trigger the overt malignant disease." (PMID 23397042, 2013). "ASXL1 is a well-established driver of a wide range of cancers." (PMID 41702923, 2026). "Furthermore, we evaluated the noncoding genome and methylome and identified inherited epimutations in genes including ASXL1, ETV6, and LEF1 that confer increased cancer risk." (PMID 37377903, 2023). "Furthermore, we leveraged the noncoding genome and methylome to identify inherited epimutations in genes including ASXL1, ETV6, and LEF1 that confer increased cancer risk." (PMID 37377903, 2023). "ASXL transcriptional regulator 1 (ASXL1), a cancer-associated gene, has been reported to hinder cell growth in CRC; however, whether circASXL1, a circRNA formed from ASXL1 gene, participates in CRC progression remains unknown." (PMID 34127015, 2021). "In contrast to the aetiology of cancers associated with mutations in BAP1, mutations in ASXL1 and ASXL2 are strongly linked to myeloid cell cancers, with ~11% of haematopoietic cancers bearing ASXL1 mutations (COSMIC)." (PMID 33105797, 2020).
cancer (continued). "The targeted NGS panel used in this study, Oncomine Pan‐Cancer, covers the most commonly detected mutations from solid tumors; however, it does not cover the genes that are commonly associated with hematopoietic stem cells, such as DNMT3A, TET2, and ASXL1." (PMID 32449983, 2020). "Here, we will discuss how somatic gene mutations in DNMT3A, ASXL1, and NPMC1 regulate the expression of HOX genes through DNA methylation and histone modifications as well as gene fusions related to HOX transcription factors driving cancer progression." (PMID 31013831, 2019). "Importantly, a cancer-associated mutation of BAP1 in its CTD, BAP1ΔR666-H669, that abrogates its interaction with ASXL1 and ASXL233, also failed in promoting DEUBAD monoubiquitination." (PMID 30349006, 2018). "In addtition, KIF3B and ASXL1 alsohave the potential to participatein human cancer." (PMID 29108255, 2017). "This could be a consequence of genetic alterations in enzymes regulating epigenetic patterns, such as gene mutations found in human myeloid malignancies, including DNMT3a, TET2, IDH1, IDH2, EZH2, or ASXL1." (PMID 24944583, 2014). "We then attempted to identify any potential associations between these PVs/LPVs (DNMT3A and ASXL1 excluded) and the clinical characteristics of MBC patients, namely, the presence of a first- or second-degree relative with cancer, personal history of cancer, BMI and smoking." (PMID 37762649, 2023). "Cancer-derived mutations are enriched in functionally important regions of BAP1—within the catalytic domain of BAP1, disrupting the catalytic triad or structural integrity of the domain; and within the ubiquitin binding site or crossover loop, disrupting the binding interface between BAP1 and ASXL1." (PMID 33105797, 2020). "In addition, we found that ASXL1 mutations are associated with DNA methylation changes in regulatory regions of cancer associated genes, not previously associated with MF." (PMID 28754985, 2017). "Our data indicate that truncated ASXL1 is associated with methylation changes of a distinct set of cancer related genes that may be involved in disease progression, although no direct link between ASXL1 and DNA methylation has yet been established." (PMID 28754985, 2017). "Genomic data from six cancer types reveals a strong positive ASXL1-BRD4 relationship, with BRD4 occupying the ASXL1 promoter and thus pointing to a possible feed-forward mechanism." (PMID 41702923, 2026). "These variants were found in over 45% of the cohort and occurred in genes with known relevance to cancer biology, including CHEK2, RAD54L, NOTCH2, ASXL1, PDGFRA, and KIT." (PMID 40627234, 2025). "As core components of the PR-DUB complex, ASXL1/2/3 and BAP1 regulate epigenetic modification of histones in various tissues and in the context of human cancer." (PMID 38366571, 2024). "Some of the amplified genes are rarely over-expressed at the mRNA level, while others, such as ASXL1, KIF3B and POFUT1, are over-expressed in most amplified cancers." (PMID 34577783, 2021). "Four cancer‐driver genes NOTCH2, ASXL1, PDE4DIP, and MUC4 were found to be selectively amplified in both hESC‐RPE and HS980 (p38) samples." (PMID 32319201, 2020). "Previous studies indicated that BAP1 might inhibit cancer cell growth by interacting with one or more partner proteins, including YY1, RBBP7, HCF-1, H2A, ASXL1/2, and FoxK1/K2." (PMID 40688406, 2025). "In addition, this case showed carcinoma-specific amplification of 7p (EGFR and BRAF) and 20q (ASXL1, AURKA, and GNAS), which were observed as clonal amplification for the three MSS cases without ERBB2 amplification." (PMID 26336987, 2015). "This dual role in cancer and development is not unique to SETBP1; a growing number of genes in which germline mutations cause developmental disorders, such as HRAS, ASXL1, EZH2 and FGFR2, are also known to harbor overlapping somatic mutations which drive the development of cancer." (PMID 28346496, 2017).
cancer (continued). "Whether the truncated ASXL1 proteins expressed in cancers and developmental disorders are functional or not remains a contentious question." (PMID 26095772, 2015). "However, in Japan, expert panels frequently discuss the possibility that ASXL1 and DNMT3A alterations may represent clonal hematopoiesis rather than somatic mutations caused by cancer." (PMID 39597083, 2024).
tumor (84 papers, 2014 to 2025). "These CHIP-related mutations, particularly in genes such as DNMT3A, TET2, and ASXL1, can be inadvertently detected in plasma cfDNA and misattributed to the tumor, resulting in false-positive findings and erroneous clinical interpretations." (PMID 40869308, 2025). "Last, Asxl1 encodes a tumor suppressor that inhibits clonal hematopoiesis through its epigenomic regulatory effects in both mice and humans." (PMID 38712036, 2025). "In mouse tumor models, Asxl1-deficient T cells exhibited strong effector activity and responsiveness to anti-PD-L1 treatment, contributing to improved tumor control." (PMID 40093905, 2025). "An ASXL1 mutation in tumor infiltrating T-cells was shown to perturb their development and function, promoting tumor growth in syngeneic animal models." (PMID 39172974, 2024). "Here we report a case of BPDCN with a novel AFF4::IRF1 fusion predicted to lead to a loss-of-function of the IRF1 tumor suppressor, somatic mutations of ASXL1, TET2, and MYD88, as well as multiple intrachromosomal deletions." (PMID 38203475, 2023). "Conditional knock-in of a tumor-derived mutation generating a C-terminally truncated Asxl1 mutant led to myeloid skewing, age-dependent anemia, thrombocytosis, and morphological dysplasia in mice." (PMID 32683582, 2021). "The tumor suppressor BAP1 associates with ASXL1/2 to form the core Polycomb complex PR-DUB, which catalyzes the removal of mono-ubiquitin from several substrates including histone H2A." (PMID 29069806, 2017). "Although ASXL1 is considered to be a tumor suppressor, the molecular mechanism underlying tumor suppression is poorly understood." (PMID 28701722, 2017). "A recent report has demonstrated that nonsense and frameshift mutations result in loss of ASXL1 expression, consistent with ASXL1 functioning as a tumor suppressor." (PMID 26623729, 2015). "On the other hand, the somatic mutations in DNMT3A and ASXL1 are of the type previously observed in other tumor types and expected to contribute to tumorigenesis." (PMID 25000259, 2014). "These therapeutic approaches could potentially be combined with other emerging therapeutic approaches such as MEK inhibitors to target RAS pathway or DNA methyltransferase inhibitors in ASXL1-mutated neoplasms." (PMID 40806796, 2025). "Variants in the CHEK2, BRCA2 and ATM tumor suppressor genes, as well as the ASXL1 and EZH2 Epigenetic Regulators, may support the self-renewal of the proliferating progenitors." (PMID 35896598, 2022). "In addition, we detected an exon 13 (c.3306G>T) ASXL1 point mutation only in the retroperitoneal tumor tissue at the time of the fourth relapse." (PMID 36050938, 2022). "Furthermore, they showed that OGT has tumor suppressive activity in myeloid malignancies, especially in the presence of ASXL1 mutations." (PMID 36104770, 2022). "For example, OGT and O-GlcNAcylation may have tumor suppressor activity early in the course of MDS and AML when ASXL1 is intact but acquire tumor promoting activity when ASXL1 is inactivated by mutation." (PMID 34868034, 2021). "As loss of ASXL1 expression through mutational inactivation seems to be coupled to a proliferative advantage in functional experiments, ASXL1 is generally considered a tumor suppressor gene." (PMID 32519264, 2021). "However, when using supervised clustering analysis in the CD34+ cells a subset of differentially methylated CpG sites, frequently located in tumor suppressors and oncogenes, were found in ASXL1 mutated cases." (PMID 28754985, 2017). "ASXL1 is also considered a tumor suppressor in other types of cancers, including that of the prostate, colorectal, and lung." (PMID 38791157, 2024). "In this study, U2AF1, DNMT3A, SF3B1, and EZH2 in the secondary tumor group was higher than that in the tumor‐free group, while the mutation rate of ASXL1, TET2, and KMT2D was higher in the tumor‐free group." (PMID 36727544, 2023).
tumor (continued). "In the TWM cases, except case 1, ARID3A, ASXL1, ASXL2, FMN2, FAM83B and ZFHX4 mutations were also identified as potential oncogenic drivers, known from other tumor types." (PMID 36980598, 2023). "Recently, BAP1 catalytic inhibitors have been developed that inhibit ASXL1‐driven leukaemic gene signatures and impaired tumour progression in an in vivo model of ASXL1 AML." (PMID 37872885, 2023). "Asxl1-mutant mRNA, along with WT Asxl1 mRNA, was found to be highly expressed in both tumor organoids." (PMID 37746286, 2023). "ASXL1 mutations are frequent, with the disease displaying a higher prevalence of ETNK1, SETBP1, and EZH2 mutations in comparison to other MDS/MPN overlap neoplasms." (PMID 37370785, 2023). "Results revealed ensuing LINC00586 overexpression abrogated the tumor suppressive effects of ASXL1 on mouse xenograft models." (PMID 35586041, 2022). "In the chemotherapy arm, early progression was associated with liver, adrenal gland or brain metastasis, or greater number of metastatic sites overall, higher SLD or tumor mutations in SMARCA, ASXL1 or CDKN2A (P < 0.05)." (PMID 35995953, 2022). "ASXL1 has already been identified as a tumor suppressor in CRC, which plays a crucial role in regulating the biological functions of CRC cells." (PMID 35586041, 2022). "BAP1 catalytic inhibitors have been shown to inhibit truncated-ASXL1-driven leukemic gene expression and halt tumor progression in vivo." (PMID 34868917, 2021). "To elucidate the mechanisms underlying the function of wild-type ASXL1 and the oncogenic role of C-terminally truncated mutant ASXL1 proteins, we set out to identify the interacting proteins of wild-type ASXL1 or tumor-derived ASXL1N646." (PMID 32683582, 2021). "Among the targets of TRIP12 is ASXL1, a tumor suppressor with roles in Polycomb-induced gene silencing." (PMID 33435458, 2021). "Here, we identified a tumor suppressor role of the acetyltransferase p300 in clinically relevant MDS models driven by mutations in the epigenetic regulators TET2, ASXL1, and SRSF2." (PMID 34622806, 2021). "The C-terminally truncated ASXL1 proteins were detected in tumor cells and were sufficient to promote the deubiquitylase activity of BAP1." (PMID 32683582, 2021). "ASXL1 is a tumor suppressor in hematologic malignancies that activates gene expression by methylating histones and forming the H3K4me3 mark associated with active transcription." (PMID 34868034, 2021). "A role for ASXL1 as a tumor suppressor was suggested by the altered gene expression by Asxl1 deletion and the upregulation of genes involved in cell-cycle progression (e.g., E2F1 target genes such as Nmyc)." (PMID 30389914, 2018). "The IDH2 (R140Q) NRAS (G13R) population shrinks to 8% of the tumor at the same relapse time point at which the triple-mutant IDH2 (R140Q) NRAS (G13R) ASXL1 (G646fs) clone expands to 64%." (PMID 30087104, 2018). "Accumulating data suggest that ASXL1 functions as a haploinsufficient tumor suppressor in the hematopoietic system." (PMID 28055972, 2017). "ASXL1 plays a role in chromatin remodelling and is a tumor suppressor gene." (PMID 37379307, 2023). "They showed that additional sex combs like transcriptional regulator 1 (ASXL1) could be stabilized by O-GlcNAcylation at Ser199, allowing it to act as a hematopoietic malignant tumor suppressor." (PMID 36104770, 2022).